DNAH5 (dynein axonemal heavy chain 5)
Diseases named in the same sentence as DNAH5 in open-access papers (continued):
Sharing a sentence is not in itself a finding about the gene and the disease.
asthma (7 papers, 2011 to 2024). "Furthermore, at least one previously associated SNP within ADCY2 and DNAH5 was associated with asthma." (PMID 21912604, 2011). "Additional genetic factors, such as genetic variations in some PCD-causing genes (DNAH14, DNAAF3, DNAH6, DNAH5, KIFC2, KIF3A), are associated with the increased risk of asthma development." (PMID 39337527, 2024). "According to transcriptomic data, DNAH5 had decreased expression in bronchial epithelium of asthma patients versus controls and in airway smooth muscle treated with budesonide 100 nM for 24 h." (PMID 35869121, 2022). "Our transcriptomic results provide evidence of the relevance of DNAH5 to asthma, given that its gene expression levels were decreased in bronchial epithelium of patients with asthma versus controls and in airway smooth muscle cells after budesonide exposure." (PMID 35869121, 2022). "We found that ADCY2, PDE4B, DNAH5 and KIF3A were again associated with asthma (p<0.05) at the gene level." (PMID 21912604, 2011). "Our investigation revealed that six of these genes (PDE4B, SPRR2B, ADCY2, KIF3A, DNAH5, and PLAU) were located in chromosomal regions that had been previously linked to asthma or other allergic disease phenotypes and had been shown to be regulated during allergic inflammation." (PMID 21912604, 2011). "One study has shown that the expression of PCD-related genes, DNAH5, KIFC2 and KIF3A, are downregulated in asthma, and that SNPs in these genes correlate with asthma and disease severity." (PMID 39337527, 2024). "In summary, by leveraging multiomics data, including capture Hi-C, gene expression, and eQTL, we found that DNAH5 may influence BDR, and its genetic variation may contribute to differences in asthma outcomes among Puerto Ricans." (PMID 35869121, 2022).
Kartagener Syndrome (7 papers, 2020 to 2025). An autosomal recessive disorder characterized by a triad of DEXTROCARDIA; INFERTILITY; and SINUSITIS. "A total of 323 PCD patients with the DNAH5 variants were included, with 14.55% of these patients were diagnosed as Kartagener syndrome." (PMID 40033371, 2025).
melanoma (7 papers, 2020 to 2025). A malignant, usually aggressive tumor composed of atypical, neoplastic melanocytes. "Recently, DNAH5 has been reported to have a mutation in melanoma, which has an important influence on melanoma development." (PMID 36891324, 2023). "In addition, Zhang and Xia reported that somatic mutations in DNAH5 contribute to the genetic etiology of melanoma." (PMID 38022557, 2023). "Among the melanoma patients, the most frequently mutated genes were TTN, MUC16, BRAF, DNAH5, and PCLO." (PMID 40781483, 2025). "Previous studies have revealed that dynein axonemal heavy chain 5 (DNAH5) is a key gene in the development and progression of some cancers, including esophageal squamous cell carcinoma, melanoma, and colorectal cancer." (PMID 38022557, 2023). "The top 10 mutated genes in melanoma were TTN (72%), MUC16 (67%), DNAH5 (49%), PCLO (44%), LRP1B (38%), ANK3 (32%), DNAH7 (32%), ADGRV1 (35%), RP1 (33%), and BRAF (51%)." (PMID 33758620, 2021). "The top 10 mutated genes in 467 melanoma patients are TTN (72%), MUC16 (67%), BRAF (51%), DNAH5 (49%), PCLO (44%), LRP1B (38%), ADGRV1 (35%), RP1 (33%), ANK3 (32%), DNAH7 (32%)." (PMID 33072607, 2020). "Of these, DNAH5 mutations in melanoma samples correlate with a negative outcome." (PMID 32241263, 2020).
colorectal cancer (5 papers, 2018 to 2023). A primary or metastatic malignant neoplasm that affects the colon or rectum. "It has been also suggested that the DNAH5 gene can play a role in the development of colorectal cancer." (PMID 35501919, 2022). "For instance, DNAH5 (dynein axonemal heavy chain 5) has an important role in the development of colorectal cancer, whereas COMP (cartilage oligomeric matrix protein) has been recently reported as a novel biomarker contributing to the severity of BC." (PMID 28981577, 2019). "For the dataset of all mutations, the cancer type-specific six gene mutation biomarkers were APC for colorectal cancer, PTEN for endometrial cancer, BRAF for thyroid cancer and MUC16, DNAH5, TTN for cutaneous melanoma." (PMID 30662873, 2018). "An integrated analysis of RNA-Seq data and qRT-PCR results revealed that DNAH5 may play an important role in the development of colorectal cancer, and it might be useful for diagnosis, prognosis prediction and therapy." (PMID 30944005, 2019).
bronchiectasis (4 papers, 2014 to 2025). Segmental, irreversible dilation of the bronchial tree resulting in the accumulation of secretions which leads to obstruction. "Individual 1, who presented with bronchiectasis and classical upper airway symptoms, carried a monoallelic missense variant in DNAH5 (c.11740G>A; p.Glu3914Lys)." (PMID 40558543, 2025). "Individual 33, a descendant of a consanguineous family, presenting with situs inversus totalis and bronchiectasis, and carried biallelic missense variants in DNAH5 (c.7615T>C; p.Trp2539Arg)." (PMID 40142748, 2025). "For example, while there was a statistically significant increase in chest pain among homozygotes for an nsSNP in DNAH5, a gene associated with respiratory ciliary disorders and bronchiectasis, the chest pain was generally attributed to external/traumatic causes rather than intrinsic lung disease." (PMID 24949630, 2014). "In accordance with the findings of this research, the majority of cases exhibited respiratory symptoms, including recurrent airway infections, sinusitis, bronchiectasis, and hearing deficits, consistent with the established function of DNAH5 in ODA formation and motile ciliary function." (PMID 40558543, 2025). "Moreover, the majority of the remaining individuals had impaired mucociliary clearance and bronchiectasis due to minimal residual or immotile cilia, and most had abnormal DNAH5 immunostaining (either negative or proximal staining pattern)." (PMID 40142748, 2025).
esophageal squamous cell carcinoma (3 papers, 2019 to 2023). Esophageal squamous cell carcinoma (ESCC) is a type of esophageal carcinoma (EC) that can affect any part of the esophagus, but is usually located in the upper or middle third. "DNAH5 mutations are common in patients with esophageal squamous cell carcinoma and are associated with poor survival." (PMID 35127708, 2021). "A previous study reported that dynein axonemal heavy chain 5 (DNAH5) mutation was associated with poor survival of patients with esophageal squamous cell carcinoma." (PMID 35127708, 2021).
respiratory infections (3 papers, 2018 to 2022). "Overall, DNAH5 mutation could decrease the immune response ability of the airway epithelium, which may account for the frequent respiratory infections in children diagnosed with PCD." (PMID 36552777, 2022). "DNAH5:p.Leu2413Pro (Condel: 0.842, CADD: 29.2) was found in a heterozygous state with heterozygous DNAAF5:p.Arg263Gln (Condel: 0) in a child with significant respiratory infections from early infancy." (PMID 34768622, 2021).
clear cell renal cell carcinomas (2 papers, 2019 to 2022). "Increased incidence of non-synonymous single-nucleotide mutations and insertions/deletions was found in DNAH2, DNAH5, and DNAH10 genes of CpG-island methylator phenotype positive clear cell renal cell carcinomas." (PMID 35501919, 2022). "DNAH2, DNAH5 and DNAH10 have been reported to have an elevated incidence of nonsynonymous single-nucleotide mutations and indels in CIMP-positive clear cell renal cell carcinomas." (PMID 30944005, 2019).
cystic fibrosis (2 papers, 2020 to 2023). Autosomal recessive disorder caused by pathogenic variants in the CFTR gene (cystic fibrosis transmembrane conductance regulator), which encodes a chloride and bicarbonate channel expressed in epithelial cells, and follow the diagnosis criteria. "Absence of mutations in DNAI1, DNAH5, and CFTR genes ruled out primary ciliary dyskinesia and cystic fibrosis." (PMID 32991486, 2020).
lung disease (2 papers, 2014 to 2025). "This genetic variant has been associated with more severe lung disease compared to genetic variants involving the outer dynein arms, such as DNAH5." (PMID 40862699, 2025).
sinusitis (2 papers, 2025). An acute or chronic inflammatory process affecting the mucous membranes of any sinus cavity. "DNAH5 was completely absent in three cases (15.7%) (CB, ÖG, and ÖY) who shared clinical characteristics: neonatal respiratory distress, chronic rhinitis, recurrent otitis and sinusitis." (PMID 40182617, 2025).
Situs inversus totalis (2 papers, 2022 to 2025). "Dynein axonemal heavy chain 17 (DNAH17) is a protein of the DNAH family of which four genes have already been associated with autosomal recessive PCD, situs inversus totalis or heterotaxy, namely DNAH1, DNAH5, DNAH9, and DNAH11." (PMID 35474353, 2022).
Arrhythmia (1 paper, 2025). Any cardiac rhythm other than the normal sinus rhythm. "Some of the genetic variants responsible for TSI can also increase the risk for arrhythmias through mutations in genes involved in the Nodal signaling pathway (NODAL and LEFTY2) and in ciliary function (DNAH5)." (PMID 41295344, 2025).
breast carcinoma (1 paper, 2020). "Additional findings that are noteworthy are that we identified the 39 most frequently mutated genes in CTCs and metastases, and some of them such as MUC16, ANKRD36, and DNAH5 are known to be biologically important in breast cancer." (PMID 32650480, 2020).
conductive hearing loss (1 paper, 2024). "Variants in CCDC114 cause sensorineural hearing loss (SNHL), while variants in CCNO, CDH3, DNAH5 and OFD1 cause conductive hearing loss (CHL)." (PMID 38818043, 2024).
congenital hydrocephalus (1 paper, 2024). Hydrocephalus that is present at birth. "In this manner, by clarifying how Dnah5 and Dync1h1 contribute to the causes and progression of congenital hydrocephalus, this research holds promise for identifying novel therapeutic targets, developing early diagnostic tools, and building a foundation for more effective personalized medicine." (PMID 39594631, 2024).
Joubert syndrome (1 paper, 2021). Joubert syndrome (JS) is characterized by congenital malformation of the brainstem and agenesis or hypoplasia of the cerebellar vermis leading to an abnormal respiratory pattern, nystagmus, hypotonia, ataxia, and delay in achieving motor milestones. "The remaining novel variants were: CCDC39:p.Glu598* (CADD, 37); CCDC40:c.1097delT (frameshift); CEP104:p.Glu698Lys (Joubert syndrome 25, Patient 9); DNAAF5:p.Val431Ala (Condel: 0.886); DNAH5 duplication of exon 1–48 (unknown significance); HYDIN:p.Pro3213Arg (likely pathogenic, Patients 17–18)." (PMID 34768622, 2021).
laryngeal carcinoma (1 paper, 2017). Carcinoma that arises from the laryngeal epithelium.
liver cancer (1 paper, 2023). An epithelial or non-epithelial malignant neoplasm that arises from the liver. "Finally, DNAH5 and pathological stage were independent prognostic factors in the TCGA dataset, whereas in the ICGC dataset, DNAH5 and Barcelona Clinic Liver Cancer (BCLC) stage were independent prognostic factors." (PMID 38022557, 2023).
lower respiratory tract infections (1 paper, 2022). "Indeed, genetic defects in DNAH5, HYDIN, and TUBA1A and others result in primary cilia dyskinesia (PCD); a variety of clinical manifestations including ineffective mucociliary clearance and recurrent lower respiratory tract infections." (PMID 35169120, 2022).
metastatic tumors (1 paper, 2016). "To determine the potential relevance of DNAH8 and DNAH5 in human prostate cancer, we examined for differences in mRNA expression among normal, primary and metastatic samples from independent validation cohorts containing 235 normal prostate, 329 primary tumor and 59 metastatic tumor cases." (PMID 27363033, 2016).
nasal polyps (1 paper, 2023). "Further, the ciliary ultrastructural marker DNAH5 is reported to be mis-localized in patients with nasal polyps and that the negative modulator of ciliogenesis cp110 is upregulated in CRSwNP patients." (PMID 37085563, 2023).
retinal diseases (1 paper, 2023). "In particular, two breathing-relatedproteins (DNAH5 and DNAH11) appear of interest because mutations ofthe genes encoding these two proteins are involved with some ciliopathiesof the respiratory tract and with retinal diseases." (PMID 37552208, 2023).
retinal dystrophies (1 paper, 2023). "On the other hand, DNAH5 has been proposed as a candidate gene for retinal dystrophies using a different method based on the aggregation of variants in unsolved cases compared to controls." (PMID 36675175, 2023).
spermatogenic failure (1 paper, 2020). A male infertility characterized by dirsuption of the process of sperm development from diploid cells into mature haploid spermatozoa. "Two pathogenic variants in two patients with primary spermatogenic failure were identified: p.Lys1853*, rs748618094 in DNAH5, and p.Asp1152His, rs75541969 in CFTR." (PMID 33574797, 2020).
supraglottic cancers (1 paper, 2020). "Conversely, we found DNAH5, which encodes a protein involved in the dynein complex and functions in ciliary cell motility to have more tobacco associated G>T transversions in the supraglottic cancers." (PMID 33396315, 2020). "DNAH5 was the only gene found to have a differential rate of G>T transversions, occurring in 20% of supraglottic carcinomas and 0% of glottic LSCC (FDR = 0.043)." (PMID 33396315, 2020).
supraglottic tumors (1 paper, 2020). "We followed up these findings by investigating the impact of NSD1 and DNAH5 on survival within the HPV-negative cohort of glottic and supraglottic tumors." (PMID 33396315, 2020).
tumor (10 papers, 2016 to 2025). "Interestingly, three genes of the dynein family of microtubule-associated motor proteins (DNAH2, DNAH3 and DNAH5) showed stopgain mutations in different post-chemotherapy residual tumor samples." (PMID 38254917, 2023). "Analysis of the mutational distribution of DNAH5 SNVs across the gene revealed a pattern suggesting the gene may function as a putative tumor suppressor given the broad distribution of the alterations and absence of hotspot sites." (PMID 33396315, 2020). "In this study, we have identified a few commonly mutated genes in pre-NACT tumor samples from either sensitive (DNAH5, CYP2D6, NUTM1) or resistant (CSPG4, TUBA3D, SLC35G5) cases, which suggest that these genes could have a potential utility for prediction of the response to NACT." (PMID 35501919, 2022). "In vitro experiments and prospective cohorts will be required to elucidate the exact role of both NSD1 and DNAH5 on LSCC tumor behavior and response to therapy." (PMID 33396315, 2020). "We conducted paired differential expression analysis to explore the differential expression of DNAH5 between HCC samples and non-tumor liver samples in the TCGA and ICGC datasets." (PMID 38022557, 2023). "DNAH5, LTF, and Ezrin were significantly increased in tumor tissues (p < 0.05), and WNT7A displayed a slight increase (p = 0.0669)." (PMID 35178403, 2021). "The results show that in the ICGC dataset, the level of mRNA expression of DNAH5 in HCC samples was significantly higher than in the non-tumor samples, but no statistical difference was found in the samples from the TCGA dataset." (PMID 38022557, 2023). "In addition, the expression profile of DNAH5, including mRNA and protein, was significantly higher in the HCC tumor tissue samples than in the normal tissue samples." (PMID 38022557, 2023).
cancer (8 papers, 2018 to 2023). A tumor composed of atypical neoplastic, often pleomorphic cells that invade other tissues. "The results showed that six cRMGs including OBSCN, CDKN2A, CSMD3, DMD, DNAH5, and KMT2Cwith MS or NS mutations have significant associations with prognosis in several cancer types." (PMID 30107644, 2018). "Mutations in DNAH5 have been associated with poorer survival in a number of different cancers." (PMID 33396315, 2020). "Most pathways of the mutant gene DNAH5 were involved in cancer development and progression based on GSEA analysis." (PMID 38022557, 2023). "Previous studies have revealed that DNAH5 is a key gene in the development and progression of some cancers." (PMID 38022557, 2023).
infection (4 papers, 2020 to 2025). The state of being infected such as from the introduction of a foreign agent such as serum, vaccine, antigenic substance or organism. "Several studies have shown that a DNAH5-deficiency always leads to immotile cilia and frequent infections in the respiratory system." (PMID 36552777, 2022). "The DNAH5 deficiency significantly decreased the expression of innate and adaptive immune systems that further affected the normal release of cytokines, while only IL-8 was increased after infection with RSV." (PMID 36552777, 2022). "Our results showed that the RSV-N gene copies in the airway organoids with the DNAH5 mutation were significantly lower than those in the control at the initial infection stage, while the RSV-N gene copies of both the RSV-infected organoids were greatly increased at 48 hpi." (PMID 36552777, 2022). "At the same time, ciliary markers such as DNAH5, DNAAF5, MCIDAS, and CCNO were downregulated following infection of hNECs." (PMID 33409274, 2020). "Interestingly, DNAH5, MCIDAS, and CCNO exhibited consistent descending trends in all infections tested, suggesting this observation to be applicable to multiple respiratory viruses." (PMID 33409274, 2020).
inflammation (1 paper, 2018). Aberrant reaction of the microcirculation characterized by movement of fluid and leukocytes from the blood into extravascular tissues. "Intriguingly, FOXJ1 localization score did not correlate with eosinophilic inflammation in NPs, which contrasted with the positive correlation between DNAH5 localization score and eosinophilic airway inflammation." (PMID 30459817, 2018).
DNAH5 also shares sentences with these, for which no sentence is quoted: Azoospermia (4 papers); ciliopathies (2); lung squamous cell carcinoma (2); viral infection (2); Adult onset (1); allergic disease (1); allergic rhinitis (1); atherosclerosis (1); bacterial meningitis (1); Batten disease (1); Burn-McKeown syndrome (1); Charcot-Marie-Tooth disease type 1A (1); childhood asthma (1); cholesteatoma (1); chronic obstructive pulmonary disease (1); chronic rhinitis (1); Coffin-Siris syndrome (1); cone-rod dystrophies (1); connective tissue disorder (1); cutaneous melanoma (1); Dextrocardia (1); endometrial cancer (1); eosinophilia (1); gastric cancer (1); hepatitis B (1); hepatocellular carcinoma (1); hypogonadism (1); hypospadias (1); Loeys-Dietz syndrome (1); lung carcinoma (1).
A further 13 diseases each share a sentence with DNAH5 in 1 paper.